TLR5 (toll like receptor 5)
Diseases named in the same sentence as TLR5 in open-access papers (continued):
Sharing a sentence is not in itself a finding about the gene and the disease.
asthma (15 papers, 2013 to 2025). "In contrast, flagellin-dependent TLR5 activation associated with HDM-induced asthma exacerbation was demonstrated." (PMID 37426425, 2023). "The data on the role of TLR5 in asthma is inconsistent, and even less is known about the effect of the genetic variants of the TLR5 rs5744174 gene on asthma susceptibility." (PMID 30623075, 2018). "The aim of this study was to investigate the association of TLR5 gene polymorphism with virus etiology and severity of bronchiolitis, and with post‐bronchiolitis asthma." (PMID 30623075, 2018). "We recruited 164 infants (age < 6 months) hospitalized for bronchiolitis in this study and determined TLR5 rs5744174 (C > T) single nucleotide polymorphism, virus etiology and severity markers of bronchiolitis, and presence of post‐bronchiolitis asthma until age 11 to 13 years." (PMID 30623075, 2018). "The effect of flagellin or its receptor, TLR5, on early-onset asthma remains elusive in humans, specifically in children, with only one study on atopic dermatitis during infancy correlating reduced risk of atopic dermatitis development to increased expression of TLR5 in cord blood." (PMID 35387053, 2021). "While the recognition of flagellin generally of TLR5 promotes inflammation in asthma, genetic variations in the TLR5 gene reveal a more complex picture, sometimes offering protection." (PMID 40672946, 2025). "The distribution across TLR5 quartiles was different (26.30% vs. 20.03%; p = 0.02 for asthma and 4.33% vs. 1.52% for COPD; p = 0.01)." (PMID 32518239, 2020). "Strikingly, patients with severe asthma (Th17-type) express lower level of TLR5 on ECs of bronchi while TLR5 expression in patients with moderate asthma is similar to healthy controls." (PMID 29867994, 2018). "The importance of epithelial TLR5 has also been observed in allergic models of asthma using flagellin as a primer for allergic responses." (PMID 23527288, 2013). "Additionally, activation of TLR5 has been found to exacerbate airway inflammation in asthma, whereas the regulatory DCs (rDCs) and Tregs can suppress TH1/TH2/TH17 responses in a TLR5-dependent manner, thereby inhibiting the development of experimental asthma." (PMID 41293166, 2025). "For example, in an asthma mouse model it has been demonstrated that a higher dose of flagellin exposure confers protection against asthma development through the induction of immunoregulatory T cells and dendritic cells (rDCs) via the TLR5 pathway." (PMID 35387053, 2021). "In conclusion, the TLR5 rs5744174 variant genotypes were associated with non‐RSV etiology of bronchiolitis, but not with the severity of bronchiolitis or with the incidence of post‐bronchiolitis asthma." (PMID 30623075, 2018). "TLR5 has recently been proposed to play a role in the immunopathogenesis of asthma." (PMID 29518161, 2018). "However, in opposition to the pro-Th2 allergic effect of TLR5, it was recently reported that administration of flagellin inhibited experimental asthma in therapeutic doses." (PMID 29867994, 2018). "Also, according to GEOprofile dataset GSE5112, PM20D1 gene expression is regulated by the TLR5 pathway, which is critically involved in allergic responses and severe asthma." (PMID 26999364, 2016). "Furthermore, we found that the expression of some molecules such as CD14, TLR5, TLR6, TLR8, TREM-1, but also IRAK-1 and IRAK-2 genes was significantly negatively associated with total serum IgE, atopic sensitization, or asthma." (PMID 24603716, 2014). "Hence, this novel observation, that TLR5 expression increases in pulmonary sensory neurons in the bleomycin-induced fibrosis model, suggests that there are different pathogenetic mechanism and clinical consequences from TLR5 function in asthma." (PMID 29518161, 2018). "We identified several significant mediation genes including INAGL1, SERPINE1, TLR5, SLC9A3 and CD9 for asthma severity and INAGL1, TLR5, CD9 for FEV1, suggesting potential regulation effect of DNAm on gene expression in asthma." (PMID 38245772, 2024).
asthma (continued). "The expressions of TLR5 and TLR7 are decreased in the epithelium of patients with severe asthma compared with healthy individuals and those with moderate asthma." (PMID 26617525, 2015). "Interestingly, another TLR5 variant (rs5744174) might increase susceptibility to bronchiolitis not caused by respiratory syncytial virus (non-RSV bronchiolitis), but this variant does not appear to be associated with the subsequent development of asthma following such bronchiolitis." (PMID 40672946, 2025). "In patients with severe asthma, a significantly negative correlation is present between intracellular TLR5 immunoreactivity and IgE." (PMID 40672946, 2025).
COVID-19 (15 papers, 2020 to 2025). A disease caused by infection with severe acute respiratory syndrome coronavirus 2. "Among the rare variants extracted, we identified some genes as candidates for COVID-19 severity, including TLR5 and SLC26A9 as well as other genes involved in the inflammatory response." (PMID 34889978, 2022). "This bias was not homogeneous across all Treg-up signature genes, a ranked plot of differential expression in each donor revealing a small subset of TregUp signature genes actually down-regulated in severe COVID-19 patients (including TLR5, ID3, and FCRL1)." (PMID 34433692, 2021). "TLR-5 expression was significantly elevated in patients with severe COVID-19." (PMID 37508529, 2023). "On the other hand, recent results using non-sterile inflammatory models in mice suggest that, during COVID-19, TLR-5 signaling might enhance SARS-CoV-2 infectivity." (PMID 37508529, 2023). "However, TLR-5 has been discussed to confer beneficial effects during viral infections such as influenza A and COVID-19." (PMID 37508529, 2023). "Interestingly, TLR4 and TLR5, which are both downregulated in COVID-19 are also essential for the germinal center response as they activate the NF-κB signaling pathway via MYD88." (PMID 33950285, 2021). "Other TLRs (TLR1, TLR4, TLR5) were also found to be downregulated in COVID-19." (PMID 33950285, 2021). "Severe COVID-19, however, is characterized by additional activation of TLR1, TLR2, TLR4, TLR5, TLR6, NOD1 and NOD2, which are primarily responsive to bacterial antigens." (PMID 36769320, 2023). "Together, these data suggest an association of MyD88 and a panel of TLRs (i.e., TLR1, TLR2, TLR4, TLR5, TLR8, and TLR9) with disease progression in patients with COVID-19." (PMID 35682644, 2022). "Parallel to the expression of MyD88, the expression of TLR1, TLR2, TLR4, TLR5, TLR8 and TLR9 was significantly elevated in patients with severe and critical COVID-19." (PMID 35682644, 2022). "Another example is the peptide vaccine against spike glycoprotein with molecular docking on toll-like receptor-5 (TLR5), which can evoke early innate immune response against COVID-19." (PMID 33364959, 2020). "In addition, the expression of TLR1, TLR4, TLR5, and TLR8 was significantly elevated in patients with severe or critical COVID-19, and the expression of TLR7 was increased in patients with moderate or critical COVID-19." (PMID 37310504, 2023). "However, our observations on TLR5, CXCL17, CCL26, IL1RL2, and IL3RA provide clear proteins to explore to explain sex differences in COVID-19 outcomes." (PMID 36171541, 2022). "Therefore, suitable TLR adjuvants, such as TLR5 adjuvant flagellin or TLR9 adjuvant CpG, could be incorporated into the genome of the novel MVA-based COVID-19 vaccine candidates." (PMID 37854858, 2023). "However, TLR5 activation may participate in severe COVID-19 complications, as these patients have increased serum levels of HMGB (a DAMP of TLR5)." (PMID 33498183, 2021). "By contrast, expression of TLR4, TLR5, TLR6, and TLR7 was not altered in COVID-19-derived monocytes." (PMID 37310504, 2023). "Consistent data indicate that TLR1, TLR5, TLR6, TLR8, NOD1, NOD2 and RIG1 are not activated in severe COVID-19." (PMID 33672738, 2021). "TLR1, TLR4, TLR5, TLR8, and TLR9 expression levels were also significantly elevated in severe and critical COVID-19 patients; however, TLR3 expression was not correlated with the development of COVID-19, and an increased expression of TLR7 was observed only in patients with moderate COVID-19." (PMID 34835108, 2021).
hyperlipidemia (12 papers, 2011 to 2025). "TLR5 has been shown to influence the serum level of HDL-C in IS patients in Chinese Han population, and it may play a role in the control of hyperlipidemia as well as atherosclerosis." (PMID 39690389, 2024).
Salmonella Infections (12 papers, 2011 to 2024). Infections with bacteria of the genus SALMONELLA. "TLR5 deficiency in mice has been associated with both increased and decreased susceptibility to WT Salmonella infections." (PMID 23977202, 2013). "The composite data also illustrate that TLR5 does not contribute to the attenuation of flgM− Salmonella, and that loss of TLR5 leads to paradoxical protection against Salmonella infection, which is most evident in the cecum." (PMID 23977202, 2013). "For example, although TLR5, a known flagellin receptor, recognizes and responds to Salmonella flagellin, and induces proinflammatory cytokines, TLR5-deficient mice show enhanced resistance against oral Salmonella infection." (PMID 26859749, 2016). "A more thorough investigation of the gut microbiota in our TLR5−/− mice may help define how TLR5-deficiency is protective against Salmonella infection." (PMID 23977202, 2013). "The mRNA expression of TLR4 and TLR5 in the ileal mucosa was significantly upregulated by Salmonella infection compared to the CON group (P < 0.05)." (PMID 39533418, 2024). "Yet, the fact that reptile and human TLR5 show a similar relative sensitivity to S. Enteritidis flagellin may suggest that flagellin recognition does not play a significant role in the differential susceptibility to Salmonella infection observed between reptiles and humans." (PMID 26738735, 2016). "Our studies demonstrate that TLR5 and caspase-1 have modest roles in host defense against wild type Salmonella infection, which is largely due to efficient FlgM-dependent silencing of flagellin expression." (PMID 23977202, 2013). "Similar to the findings of the Gewirtz’s and Akira’s groups, we found that TLR5−/− mice have lower CFU in the cecum during WT Salmonella infection." (PMID 23977202, 2013). "Alexopoulo and colleagues found that TLR5 protected mice against Salmonella infection, but that this function was largely masked by TLR4." (PMID 23977202, 2013). "Typhimurium is capable of activating the innate immune system via a specific interaction with TLR5 to elicit immune protection to Salmonella infection." (PMID 24069357, 2013). "Akira and colleagues demonstrated that TLR5 recognition of flagellin promoted Salmonella infection and systemic spread." (PMID 23977202, 2013). "In the present work, we observed that probiotic administration increased TLR5 (+) cells after Salmonella infection in both groups that received the probiotic strain for 7 days post challenge compared to untreated mice." (PMID 21813005, 2011). "Thus the role of TLR5 in mucosal Salmonella infection is complex, and involves both homeostatic interactions with gut commensals that influence microbial composition and immune status, and detection of flagellated pathogens." (PMID 23977202, 2013). "The role of TLR5 during Salmonella infection is controversial." (PMID 23977202, 2013). "The high expression of TLR5 in neonates may not contribute to protection against pathogens as neonatal TLR5 knockout mice did not exhibit increased susceptibility to Salmonella infection." (PMID 36090061, 2022). "Therefore, it is postulated that B. pseudomallei flagellin may also promote humoral immunity via a TLR5-independent pathway similar to that reported during Salmonella infection." (PMID 28475641, 2017). "Thus TLR5 promotes Salmonella infection independently of flagellin expression by Salmonella." (PMID 23977202, 2013). "The results revealed that Salmonella infection up-regulated all studied pro-inflammatory cytokines such as TNF-α, IL-8, IL-6 and TLR4, TLR5 signaling pathways, while decreasing the expression of TGF-β." (PMID 36556320, 2022). "Typhimurium are capable of activating the innate immune system via specific interactions with TLR5 and NLR that lead to immune protection against Salmonella infection." (PMID 24069357, 2013).
Salmonella Infections (continued). "Gewirtz and colleagues demonstrated that loss of TLR5 led to an increased basal inflammatory state and non-specific resistance to Salmonella infection, suggesting that TLR5 interactions with the intestinal microbiota may promote Salmonella infection." (PMID 23977202, 2013). "Further studies are required to elucidate how TLR5 influences Salmonella infection in the absence of flagellin expression by Salmonella." (PMID 23977202, 2013). "Stimulation of TLR5 by extracellular flagellin induced the secretion of proinflammatory cytokines following NF-κB activation and chemokine production, while flagellin within the cytosol of host macrophages is detected through the NLR during Salmonella infection." (PMID 24069357, 2013). "Similar to WT Salmonella infection, bacterial burden in the spleen, liver and MLN was indistinguishable between WT and TLR5−/− mice, indicating that the attenuation mediated by flgM deficiency is not due to flagellin detection by TLR5." (PMID 23977202, 2013).
autoimmune disease (11 papers, 2012 to 2024). A disorder resulting from loss of function or tissue destruction of an organ or multiple organs, arising from humoral or cellular immune responses of the individual to their own tissue constituents. "Activation of TLR5, located on the cell membrane surface, by flagellin results in activation of the NF-kB pathway, which is linked to cancer, inflammatory and autoimmune diseases." (PMID 31083432, 2019). "Intriguingly, over the recent decades in Western societies, concurrently to the overall reduction of infectious diseases and the consolidation of the TLR5 C-variant in the human genome, epidemiological data provided evidence of a steady rise of autoimmune diseases." (PMID 31083432, 2019). "However, while TLR5 loss in humans is linked positively to infection sensitivity, it is linked negatively with autoimmune disease, which may signify a cost from using the system to control the microbiota that can drive its loss." (PMID 35732630, 2022). "The new findings indicate that TLR5 influences important regulatory functions of the immune system, and more studies on its role in autoimmune diseases are required." (PMID 38791389, 2024). "Despite the importance of TLR5 in host defenses, the extensive activation of TLRs may contribute to inflammatory and autoimmune diseases." (PMID 36139809, 2022). "Comparison of rules for each disease revealed that TLR3, TLR5, IL18, IL18R1, and IL1R1 genes occurred in rules for all studied diseases, showing good discriminant power among studied autoimmune diseases as visualized by the Andrews curves." (PMID 31396542, 2019).
Autoimmunity (11 papers, 2014 to 2024). The occurrence of an immune reaction against the organism's own cells or tissues. "While there is a paucity of data regarding the role of TLR5 in SS (and in autoimmunity in general), TLR5-dependent signaling pathways may contribute to disease." (PMID 30671484, 2018). "Further studies of TLR5 in peripheral blood samples and salivary tissue of pSS patients may reveal an important role for this poorly understood receptor in autoimmunity." (PMID 30671484, 2018). "Toll-like receptors (TLRs) play critical roles in the activation of innate immunity and we have previously shown that antibody triggering of TLR4 and TLR5 may contribute to autoimmunity." (PMID 25514237, 2014).
colorectal cancer (10 papers, 2013 to 2024). A primary or metastatic malignant neoplasm that affects the colon or rectum. "In our previous work, we showed that functional alleles correlated with survival—the frequent TLR5 SNPs are associated with altered survival in a large cohort of Caucasian patients with colorectal cancer." (PMID 36140341, 2022). "In the present study, 1036 DNA samples were genotyped SNP for rs5744168 as well as for a missense mutation SNP, rs2072493, which is located in a TLR5 exon and is reportedly associated with decreased survival in colorectal cancer." (PMID 29179462, 2017). "Based on our previously obtained results on colorectal cancer, we hypothesized that selected polymorphisms in TLR5 gene could be associated with COPD and/or LC predisposition and potentially recognized as yet unknown biomarker of LC development in the patients diagnosed with COPD." (PMID 36140341, 2022). "A recent study also highlighted a correlation between elevated TLR5 expression in tumor tissues and a more favorable prognosis for colorectal cancer patients." (PMID 38630304, 2024). "Using the MC-38 colorectal cancer mouse model, we examined the outcome of anti-tumor treatments using either TLR5 agonist or anti-PD-1 monotherapy, and both agents in combination." (PMID 38630304, 2024). "Concerning the prevalent single-nucleotide polymorphisms (SNPs) in TLR5, research has been conducted to understand the link between TLR5 genotype and the survival rate of colorectal cancer patients." (PMID 38630304, 2024). "TLR5 is receptor for flagellin, the promoter of the bacterial flagellum and has been studied in the context of colorectal cancer." (PMID 36140341, 2022). "A study in a rat model of colorectal cancer evaluated the effect of administering toll-like receptor 4 (TLR4) lipopolysaccharide (LPS) or toll-like receptor 5 (TLR5) agonist flagellin after radiation." (PMID 36230500, 2022). "Previous studies have reported that the Toll-like receptor family members TLR3, TLR4, and TLR5 were up-regulated in colorectal carcinoma tissues." (PMID 23866094, 2013). "Moreover, we confirmed the therapeutic potential of the TLR5 agonist and anti-PD-1 therapy in CT-26 colorectal cancer cells." (PMID 38630304, 2024). "Our analysis confirmed that TLR5 agonist monotherapy could attenuate the proliferation of MC-38 colorectal cancer cells, suggesting that treatment with a TLR5 agonist alone triggers an anti-tumor immune response against colorectal cancer." (PMID 38630304, 2024). "An absence of TLR5 in tumor cells, as observed in mouse xenografts of human colorectal cancers, promotes tumor growth and reduces tumor necrosis." (PMID 38630304, 2024).